BDNF (brain derived neurotrophic factor)
Diseases named in the same sentence as BDNF in open-access papers (continued):
Sharing a sentence is not in itself a finding about the gene and the disease.
Huntington disease (continued). "In models of Huntington's disease, mutant huntingtin protein interferes with the TORC1-CREB interaction to repress transcription of brain-derived neurotrophic factor, and also the depletion of CRTC1 contributes to Huntington's disease." (PMID 27034888, 2016). "BDNF overexpression in a Huntington’s disease mouse model was previously shown to prevent the decrease of striatal VGLUT1, but that effect most likely resulted from a neuroprotective mechanism of BDNF, which may have precluded the loss of glutamatergic synapses." (PMID 23326507, 2013). "For example, in Huntington's disease, excessive levels of REST are found in the nucleus, repressing target genes such as BDNF and resulting in neurodegeneration." (PMID 22496669, 2012). "Moreover, alteration of BDNF signalling has been shown in other neurodegenerative diseases including amyotrophic lateral sclerosis (ALS) and Huntington's disease (HD)." (PMID 38752280, 2024). "Similarly, the use of A-971432, a selective S1PR5 agonist, preserves BBB integrity and activates pro-survival pathways, such as brain-derived neurotrophic factor (BDNF), Akt, and ERK, in an animal model of Huntington’s disease." (PMID 37628815, 2023). "BDNF exerts neuroprotective effects on NMDA-dependent toxicity, and NMDA receptor-mediated excitotoxicity is hypothesized to be involved in Huntington’s disease pathogenesis." (PMID 35743271, 2022). "This suggests that defects in synaptic plasticity do not depend on cortical delivery of BDNF on striatal spiny projection neurons, at least early in Huntington’s disease." (PMID 28280960, 2017). "Along with BDNF, genes like BCL2 and G-protein coupled receptors (GPCRs) could also be part of therapeutic measures in Huntington's disease." (PMID 27924190, 2016). "Unexpectedly, while enhanced BDNF/TrkB signaling mechanisms have previously been described to underlie disease ameliorating fingolimod actions, e.g., in mouse models of Rett syndrome and Huntington’s disease, such BDNF/TrkB mechanisms have not been observed in AD mice." (PMID 37014414, 2023). "Pridopidine has also been found to increase brain-derived neurotrophic factor (BDNF) signaling, improve motor function and extend the lifespan of Huntington's disease model mice, and may exert Sigma-1R-dependent neuroprotective effects in neurons from such mice." (PMID 29692729, 2018). "Drugs that are able to increase BDNF level in the brain include antidepressants e.g. lithium increases BDNF concentrations in serum by 30%, and ampakines increase BDNF and improve stabilization of LTP and long-term memory in a mouse model of Huntington’s disease." (PMID 23320097, 2013).
neuroblastoma (208 papers, 2005 to 2026). Neuroblastoma (NB) is the most common solid, extracranial childhood tumor. "Elevation of BDNF has been associated with poor prognosis in neuroblastoma and has been shown to increase tumor cell viability via BDNF-mediated activation of tropomyosin receptor kinase B (TrkB) signaling in gynecologic cancer cells." (PMID 36077609, 2022). "The suppression of neuroblastoma progression caused by DLX6‐AS1 silencing can be reversed by overexpression of BDNF or knockdown of miR‐107." (PMID 35592755, 2022). "Brazilian green propolis has been shown to protect SH-SY5Y neuroblastoma cells from neurodegenerative damage by upregulating brain-derived neurotrophic factor (BDNF) and activity-regulated cytoskeleton-associated protein (ARC), proteins involved in memory." (PMID 34444688, 2021). "Overexpression of tau protein also caused the downregulation of the BDNF expression in human neuroblastoma cells and transgenic mice." (PMID 34071978, 2021). "Stepwise treatment with retinoic acid and BDNF caused the neuroblastoma cells to grow extended and branched neurites with apparent resemblance to neurons." (PMID 29312956, 2017). "Brain-derived neurotrophic factor (BDNF) and its tyrosine kinase receptor TrkB have been reported to be associated with poor prognosis in neuroblastoma (NB) patients." (PMID 27752996, 2016). "TrkB and its ligand BDNF are highly expressed in biologically unfavourable neuroblastomas, and TrkB expression is associated with drug resistance and expression of angiogenic factors." (PMID 22269274, 2012). "BDNF has been implicated in the pathogenesis and prognosis of numerous human malignancies such as neuroblastomas, medulloblastoma, prostate cancer, lung cancer, pancreatic carcinoma, and hepatocellular carcinoma." (PMID 21966426, 2011). "For example, for BDNF, which is associated with neuronal cell growth, PFOS increased the expression of BDNF-associated miRNAs in human neuroblastoma cells and altered the methylation levels of BDNF promoters I and IV, significantly reducing BDNF mRNA expression and protein levels." (PMID 37505537, 2023). "Importantly, expression of TrkA and TrkC is positively correlated with favorable biological features of neuroblastoma, whereas increased expression of TrkB and BDNF is associated with an unfavorable prognosis in patients concomitant with MYCN-amplification." (PMID 36831211, 2023). "Using human neuroblastoma cells as a model, they attributed the effects to anti-oxidative properties of propolis, expression of brain-derived neurotrophic factor (BDNF), and activity-regulated cytoskeleton-associated protein (Arc), as being the critical factors of synapse efficacy." (PMID 35011307, 2021). "In addition, high-risk neuroblastoma also expresses the TrkB ligand brain-derived neurotrophic factor (BNDF) resulting autocrine/paracrine tumor cell survival." (PMID 30760980, 2019). "Overexpression of BDNF and TrkB is also associated with poor outcomes for neuroblastoma patients." (PMID 22911740, 2012). "For instance, the literature data suggests that high BDNF levels might be associated with malignant disease progression and cancer cell survival, and our previous studies showed that BDNF improves the recovery of damaged neuroblastoma cells." (PMID 37864014, 2023). "For example, several reports demonstrate that aripiprazole increases brain-derived neurotrophic factor (BDNF) and decreases pro-apoptotic processes in neuroblastoma cells, rat neuron cultures, and activated microglia." (PMID 39937830, 2025). "Our study investigated the electrophysiological changes in SH-SY5Y human neuroblastoma cells following long-term differentiation induced by RA/BDNF treatment." (PMID 40559208, 2025). "This study aimed to compare RA/BDNF-treated human neuroblastoma SH-SY5Y cells with untreated controls, exploring their potential as an in vitro model to investigate the characteristics of NMDA receptor-mediated currents and action potentials." (PMID 40559208, 2025).
neuroblastoma (continued). "One study found that BDNF/p75NTR regulated FAS-induced apoptosis in human neuroblastoma cells, underscoring this regulatory network’s importance for neuronal health." (PMID 40430064, 2025). "SH-SY5Y neuroblastoma cells can be effectively differentiated into a neuronal phenotype using retinoic acid (RA) and brain-derived neurotrophic factor (BDNF), making them a valuable in vitro model for studying neuronal differentiation." (PMID 40559208, 2025). "Further, Tagai and colleagues found that increased BDNF levels prevent AD-like features and inhibited caspase-6 activation in neuron-like differentiated human neuroblastoma SH-SY5Y cells." (PMID 40430064, 2025). "In this study, we demonstrate that ES outperforms BDNF in promoting neuronal maturation in human neuroblastoma SH-SY5Y." (PMID 39922942, 2025). "First, SH-SY5Y neuroblastoma cells were differentiated into cholinergic neuron-like cells using all-trans retinoic acid (RA) and brain-derived neurotrophic factor (BDNF)." (PMID 40445481, 2025). "In the case of non-small cell lung cancer, BDNF treatment has been shown to counteract cisplatin-induced cell death and reduce the chemosensitivity of neuroblastoma cells to cisplatin, with a role of PI3K implicated in BDNF's effects." (PMID 38592583, 2024). "Theseresults contradict previous findings indicating that amisulprideincreases BDNF levels in human neuroblastoma SH-SY5Ycells." (PMID 39027123, 2024). "Studies have shown that BDNF promotes vascular neogenesis by recruiting TrkB‐expressing active endothelial stem cells and promoting chemotherapy resistance in neuroblastoma cells." (PMID 39648800, 2024). "We observed a dose-dependent increase in BDNF expression in human neuroblastoma SHSY5Y cells upon treatment with OC." (PMID 38835076, 2024). "The OR between remission and relapsed groups was used Logistic regression analysis: OR = 3.359; 95% CI: 1.297–8.701 (P = 0.014),so serum BDNF were identified as predictors of relapse in neuroblastoma children." (PMID 37460933, 2023). "Then, the effect of PEMs and PEM containing BDNF on the viability and morphology of neuroblastoma cells was evaluated." (PMID 37864014, 2023). "We found enhanced expression of Arc dimer in carbachol treated neuroblastoma cells, BDNF treated cortical neuronal cultures, and following in vivo LTP induced by HFS of perforant path input or intrahippocampal infusion of BDNF." (PMID 37363319, 2023). "In neuroblastoma, BDNF expression protects cells from chemotherapy-induced apoptosis via PI3K and also increases metastasis formation via the PI3K and MAPK pathways." (PMID 38188020, 2023). "Alternative benefits elicited by BDNF were also indicated by a reduction of cholesterol-induced apoptotic activity (programmed cell death) in the neuroblastoma cell line SH-SY5Y." (PMID 36835623, 2023). "The application of BDNF-PEM coacervates was tested in the environment of human neuroblastoma cell line SH-SY5Y." (PMID 37864014, 2023). "We previously reported that decreasing levels of brain‐derived neurotrophic factor (BDNF) promoted beta‐amyloid (Aβ)‐induced neuronal cell death in neuron‐like differentiated SH‐SY5Y (ndSH‐SY5Y) human neuroblastoma cells in an AD mimic cell model." (PMID 35592293, 2022). "BDNF treatment abolished cisplatin-induced cell death and reduced the chemosensitivity of neuroblastoma cells to cisplatin, an effect that was blocked by treatment of cells with the PI3K inhibitor, LY294002, indicating a role of PI3K in BDNF’s rescue effects." (PMID 36361620, 2022). "It has been confirmed that miR‐107 was the downstream target of DLX6‐AS1, and miR‐107 targeted an oncogene in neuroblastoma named brain‐derived neurotrophic factor (BDNF)." (PMID 35592755, 2022). "Abnormal BDNF/TrkB signal increases the possibility of tumour formation in the nervous system, such as neuroblastomas, glioma, and medulloblastomas." (PMID 36497280, 2022).
neuroblastoma (continued). "A decrease in the S phase was observed by Encinas and coworkers when SH-SY5Y neuroblastoma cells, treated with RA (10 μM) and BDNF (50 ng/ml), transdifferentiated into homogenous neuronal-like cells." (PMID 36106176, 2022). "It has been studied that elevated BDNF can mitigate the neuronal and synaptic injury in AA-exposed human neuroblastoma (NB-1) cells." (PMID 35651724, 2022). "We have recently reported that VPA downregulates TrkB expression and signaling and impairs the prosurvival activity of BDNF in human neuroblastoma cells." (PMID 34360553, 2021). "The SH-SY5Y neuroblastoma cells are differentiated with an artificially high level of BDNF (50 ng/mL), which is much lower in the interstitial space of the brain under physiological or pathological states." (PMID 33324339, 2020). "The effects of LicA on BDNF expression were examined in three other cell lines: neuroblastoma TGW, colorectal SW480, and cervical HeLa S3." (PMID 31941116, 2020). "To determine if LicA inhibits transcription of TrkB and BDNF mRNA, we constructed reporter plasmids covering the promoter region of each gene and performed reporter gene assays in two neuroblastoma cell lines, SK-N-SH and TGW, and a CRC cell line, SW480." (PMID 31941116, 2020). "The exposure of human neuroblastoma cells to VPA reduced the expression of the brain-derived neurotrophic factor (BDNF) receptor tropomyosin-related kinase receptor B (TrkB)." (PMID 32466248, 2020). "The expression of BDNF, its receptor and a high degree of vascularization are poor prognosis factors in neuroblastoma." (PMID 32183322, 2020). "Brain-derived neurotrophic factor activation of TrkB induces vascular endothelial growth factor expression via hypoxia-inducible factor-1alpha in neuroblastoma cells." (PMID 32876194, 2020). "This study shows that taurine and ginsenoside Rf act synergistically to increase the expression of brain-derived neurotrophic factor (BDNF) in SH-SY5Y human neuroblastoma cells in a dose- and time-dependent manner." (PMID 32570881, 2020). "TrkB and its high-affinity ligand brain-derived neurotrophic factor (BDNF) had originally been recognized as notable markers for poor prognosis in neuroblastoma and as key players for its progression." (PMID 31941116, 2020). "The results of the present study demonstrated that the ginseng-derived medicinal compound g-Rf and taurine synergistically increased the expression of BDNF in human neuroblastoma cells." (PMID 32570881, 2020). "Another study proved that As can reduce mitochondira membrane potential (MMP) and decrease BDNF gene expression in As treated human neuroblastoma SH-SY5Y cells." (PMID 31199848, 2019). "We then tested the AD GAG capacities to potentiate BDNF neuritogenic activity in neuroblastoma SH-SY5Y cells." (PMID 30608949, 2019). "It was previously reported that PACAP upregulated BDNF expression in primary neuronal cultures from rat cerebral cortex, as well as in human neuroblastoma cells upon injury." (PMID 31192159, 2019). "Pridopidine has also been found to enhance the secretion of BDNF in a neuroblastoma cell line in a S1R-dependent manner." (PMID 30756361, 2019). "This alternative mechanism is also supported by the fact that pridopidine induces BDNF release in neuroblastoma cells." (PMID 29783994, 2018). "The pro-domain of BDNF protein exerted toxic effects only in the presence of Aβ in SH-SY5Y human neuroblastoma cells." (PMID 30463271, 2018). "TrkB and BDNF co-expression is detected in more aggressive neuroblastomas especially with MYCN amplification." (PMID 30034627, 2018). "Expression of truncated TrkB, that is generated by alternative splicing and serves as a decoy for BDNF, correlates with a more favourable outcome in neuroblastoma patients." (PMID 30034627, 2018).
neuroblastoma (continued). "In earlier studies, the secretion of MMPs has been proposed to make a significant contribution to the BDNF-induced cancer invasiveness of neuroblastoma and lung large cell neuroendocrine carcinoma." (PMID 28800782, 2017). "The role of BDNF in the regulation of cell survival/growth has been described elsewhere regarding breast cancer, neuroblastoma and myeloma and these effects have been found to occur in both an autocrinal and a paracrinal manner." (PMID 28800782, 2017). "We previously demonstrated that SK-N-BE neuroblastoma cells differentiated with 9-cis retinoic acid show higher production of BDNF and its receptor, TrkB." (PMID 27256407, 2016). "Concerning the role of BDNF in neuroblastoma tumours, previous studies suggested that BDNF and its receptor TrkB are involved in an autocrine loop that promotes cell survival and resistance to chemotherapy." (PMID 27256407, 2016). "BDNF protein was clearly detected as bright fluorescent spots inside neuroblastoma cells (BDNF in green, actin in red)." (PMID 27256407, 2016). "For instance, oligomeric Aβ peptide downregulates BDNF levels via Aβ-induced CREB transcriptional downregulation in human neuroblastoma (SH-SY5Y) cells." (PMID 27094739, 2016). "In this study we found that cisplatin-induced cytotoxic stress was able to stimulate BDNF production in the MYCN-amplified neuroblastoma cell line SK-N-BE by enhancing both transcription and translation of multiple BDNF mRNAs." (PMID 27256407, 2016). "The activation of TrkB by BDNF has been suggested to enhance neuroblastoma cell survival and resistance to chemotherapy." (PMID 26518675, 2016). "DISS protects human neuroblastoma cells (SH-SY5Y) from Glu- or H2O2-induced damage, and DISS-mediated regulation of BDNF expression is associated with CREB-mediated transcription of BDNF and upstream activation of ERK1/2 and CaMKII." (PMID 27729863, 2016). "In conclusion, this analysis revealed a clear enrichment of BDNF spots in surviving neuroblastoma cells after 24 h of combined treatment with cisplatin and PHA-680632." (PMID 27256407, 2016). "High levels of TrkA and TrkC is expressed in biologically favourable neuroblastoma while high levels of TrkB and its ligand BDNF is expressed in biologically unfavourable aggressive neuroblastoma with MYCN amplification." (PMID 26010602, 2015). "In neuroblastoma, brain-derived neurotrophic factor (BDNF) activates the PI3K/Akt pathway resulting in suppression of FoxO3a activity and Bim induction, thereby preventing paclitaxel-induced apoptosis." (PMID 26405162, 2015). "SH-SY5Y human neuroblastoma cells were exposed to various concentrations of PFOS to examine the role of the BDNF-ERK-CREB signalling pathway in PFOS-induced apoptosis and cytotoxicity." (PMID 26649298, 2015). "Consistently, Garzon and Fahnestock have reported that oligomeric Aβ1–42 can decrease BDNF transcripts IV and V in a human neuroblastoma cell line." (PMID 25849905, 2015). "A recent study demonstrated that arsenic reduced BDNF expression in human neuroblastoma SH-SY5Y cells." (PMID 26368803, 2015). "This protective effect of BDNF was also evidenced in bone marrow-derived SH-SY5Y neuroblastoma cells exposed to the neurotoxin HIV-1 Tat." (PMID 24505242, 2014). "To verify the potential relevance of our observations to neuronal signaling, we assessed the ability of BDNF to induce TRKB phosphorylation in a human neuroblastoma-derived cell line, SH-SY5Y." (PMID 24867303, 2014). "In contrast, high intratumoral expression of NTRK2 and its specific ligand, brain-derived neurotrophic factor (BDNF), enhances proliferation, metastatic behavior and chemoresistance in neuroblastoma cells." (PMID 25361003, 2014). "In neuroblastoma, TrkB/BDNF expression is preferentially found in aggressive tumors, whereas the expression TrkA or TrkC is associated with better prognosis." (PMID 24959744, 2014).